CX3CL1 (C-X3-C motif chemokine ligand 1)
Diseases named in the same sentence as CX3CL1 in open-access papers (continued):
Sharing a sentence is not in itself a finding about the gene and the disease.
rheumatoid arthritis (32 papers, 2012 to 2025). A chronic, systemic autoimmune disorder characterized by inflammation in the synovial membranes and articular surfaces. "According to several studies, CX3CL1 has a significant impact on the inflammation associated with rheumatoid arthritis." (PMID 38590803, 2024). "Diabetes mellitus and rheumatoid arthritis are systemic diseases that are associated with an increased amount of CX3CL1 and CX3CR1, providing good evidence for their role in the chronic inflammatory process and pathogenesis of bone resorption." (PMID 38590803, 2024). "Quetmolimab, a humanized anti-CX3CL1 monoclonal antibody, is undergoing clinical trials for the treatment of various inflammatory diseases, including rheumatoid arthritis and Crohn disease." (PMID 40458609, 2025). "Elevated tissue and serum expression of CX3CR1 and CX3CL1 can be observed in rheumatoid arthritis (RA) and Sjogren's syndrome, affirming this chemokine participation in recruiting inflammatory cells in target organs." (PMID 39392260, 2024). "Higher soluble and membrane-bound levels of CX3CL1 and CX3CR1 have been found in the serum of rheumatoid arthritis patients, suggesting that CX3CL1 is the main factor that drives inflammation through the recruitment of monocytes." (PMID 38590803, 2024). "For Scopus, the search strategy was: (“periodontitis”/AND “rheumatoid arthritis”/AND “CX3CL1”/AND “CX3CR1”)." (PMID 38415821, 2024). "(E) Migration assay of synovial leukocytes from patients with rheumatoid arthritis after stimulation with sFasL or CX3CL1 (n = 4)." (PMID 34223817, 2021). "(D) Levels of chemokines in supernatants of synovial leukocyte cultures from patients with rheumatoid arthritis, measured using ELISA after treatment with CX3CL1 (n = 6)." (PMID 34223817, 2021). "CX3CL1 is expressed by macrophages and FLSCs in the synovial tissue of patients with rheumatoid arthritis and plays a critical role in animal models of arthritis." (PMID 34223817, 2021). "Higher levels of soluble CX3CL1 are observed in different inflammatory disorders like asthma, rheumatoid arthritis or osteoarthritis, where CX3CL1 is responsible for chemotaxia of leukocytes, NK cells, and T-cells at the site of inflammation." (PMID 33496844, 2021). "A humanized anti-CX3CL1 mAb E6011 has been tested in a phase 1/2 clinical trial in patients with rheumatoid arthritis showing good tolerability and safety." (PMID 30845779, 2019). "Most notably, a humanized monoclonal antibody against CX3CL1 has also been found to be safe and well-tolerated in the clinic when used in Rheumatoid Arthritis and Crohn’s Disease patients." (PMID 29230166, 2017). "In rheumatoid arthritis, macrophages, fibroblasts, endothelia and dendritic cells expressed high Cx3cl1 levels." (PMID 26582142, 2015). "An anti-CX3CL1 monoclonal antibody showed promise for rheumatoid arthritis in early trials." (PMID 41269996, 2025). "In inflammatory diseases, CX3CL1 is released not only by the endothelium but also by monocytes, T lymphocytes, and NK cells as shown for rheumatoid arthritis and cardiovascular diseases and further enhances the recruitment of inflammatory cells from the circulation." (PMID 28260841, 2017). "Serum CX3CL1 was also increased in asthma, scleroderma, and rheumatoid arthritis." (PMID 22394569, 2012). "DC32, a dihydroartemisinin derivative, was found to significantly inhibit the transcription of chemokines (CXCL12 and CX3CL1) and IL-6 in rheumatoid arthritis (RA)." (PMID 34956376, 2021). "Treatment with anti-CX3CL1 mAb (a neutralizing antibody) can prevent macrophage migration into the synovium of rheumatoid arthritis (RA) in a murine model, and humanized anti-CX3CL1 mAb has been used to treat patients with RA." (PMID 33505961, 2020). "This systematic review aimed to investigate the role of the Fractalkin‐CX3CL1/CX3CR1 axis as pro‐inflammatory biomarkers to distinguish between periodontitis and rheumatoid arthritis and/or systemically healthy subjects." (PMID 38415821, 2024).
rheumatoid arthritis (continued). "Mechanistically, these expanded inflammatory Thy1+ fibroblasts were shown to drive inflammation in rheumatoid arthritis by secreting IL6 and chemokines such as CCL2, CX3CL1, CXCL9, and CXCL12." (PMID 35085231, 2022). "The same authors also evaluated the expression of CX3CL1 and its receptor in peripheral blood samples and synovial fluid of patients with RA, osteoarthritis, juvenile rheumatoid arthritis, psoriatic arthritis, polyarthritis, spondyloarthropathy, inflammatory myopathy, and gout." (PMID 28546658, 2017). "Furthermore, as a secondary objective, we determine whether the CX3CL1/CX3CR1 axis could be considered complementary to clinical parameters to distinguish between periodontitis and rheumatoid arthritis (RA) and/or systemically healthy subjects." (PMID 38415821, 2024). "Our findings are in agreement with previous reports that demonstrated CX3CL1, but not CXCL16 induction by TNF-α in rheumatoid arthritis synovial tissue fibroblasts." (PMID 33552057, 2020).
Stroke (32 papers, 2013 to 2025). Sudden impairment of blood flow to a part of the brain due to occlusion or rupture of an artery to the brain. "According to recent reports, when inhibition of CX3CR1 is targeted early, or CX3CL1 expression levels are increased, administration of exogenous CX3CL1 after ischemia can reverse the neurological damage caused by stroke to some extent." (PMID 34276530, 2021). "Elevated plasma CX3CL1 has been associated with better human stroke outcomes." (PMID 39624169, 2024). "Likewise, we and others described an inverse association of Fractalkine/CX3CL1 dynamics with clinical severity and outcome in stroke patients." (PMID 33319833, 2020). "In summary, the CX3CR1/CX3CL1 signaling axis serves as the central regulatory mechanism for post-stroke brain repair." (PMID 40722349, 2025). "This review delineates the core pathophysiological signature of stroke-induced CX3CR1/CX3CL1 signaling: its spatiotemporally evolving dual neurotoxic/neuroreparative effects." (PMID 40722349, 2025). "Within hours of stroke onset, neurons in the ischemic core undergo rapid disintegration, releasing abundant soluble CX3CL1." (PMID 40722349, 2025). "Post-stroke immune responses through CX3CL1 levels were assessed from day 1 to day 180 in a cohort of 85 patients." (PMID 34831273, 2021). "On the contrary, exogenous administration of CX3CL1 has also been shown to be protective during stroke in mice." (PMID 33058417, 2020). "Choroid plexus tissues were collected and analyzed for Vcam1, Madcam1, Cx3cl1, Ccl2, Nt5e, and Ifnγ expression at different timepoints after stroke using qPCR." (PMID 28754163, 2017). "At 1 day after stroke, Vcam1, Madcam1, and Cx3cl1 showed upregulation (Vcam1, Madcam1, and Cx3cl1), and this change of Cx3cl1 expression remained 2 days later (Cx3cl1)." (PMID 28754163, 2017). "The CX3CR1/CX3CL1 axis exhibits phase-dependent functional duality, with its cellular sources, signaling intensity, and biological consequences evolving across stroke progression, exhibiting both neuroprotective and neurotoxic manifestations at different stages." (PMID 40722349, 2025). "ge Y administered exogenous rCX3CL1 to mice with cerebral ischemia-reperfusion and found that rCX3CL1 could inhibit CX3CL1 signaling pathway can be used as a therapeutic target to promote functional recovery after stroke." (PMID 39206161, 2024). "Whether CX3CL1 could mediate microglia polarization to influence the outcome of stroke is also a problem." (PMID 35990892, 2022). "Contrary to the original hypothesis, patients with better clinical outcome 6 months post-stroke had higher levels of CX3CL1 in blood plasma." (PMID 34831273, 2021). "Several studies have focused on the involvement of the CX3CL1/CX3CR1 pathway in stroke pathophysiology, presenting ambiguous conclusions on whether activation of the chemokine cascade possesses a neuroprotective or detrimental role." (PMID 34417725, 2021). "In a clinical study, researchers hypothesized that patients with higher plasmatic levels of CX3CL1 after stroke would have a more robust inflammatory response and would have worse functional outcomes." (PMID 34831273, 2021). "However, both detrimental and beneficial effects have been attributed to CX3CR1/CX3CL1 signaling in stroke." (PMID 33058417, 2020). "However, other studies support a protective effect of CX3CL1 in stroke." (PMID 34831273, 2021). "In addition, the CX3CL1/CX3CR1 chemokine pathway is involved in stroke pathology." (PMID 34417725, 2021). "Thus, the interactions between neurons and microglia, mediated by the CX3CL1/CX3CR1 pathway could be essential in the pathology of stroke." (PMID 24722201, 2014). "In stroke management, precise pathological staging is fundamental for targeted CX3CR1/CX3CL1 modulation and essential for elucidating disease mechanisms, optimizing therapies, and predicting outcomes." (PMID 40722349, 2025).
Stroke (continued). "As stroke pathology progresses into the acute phase (24 h–7 d), the CX3CR1/CX3CL1 axis undergoes critical spatiotemporal reprogramming." (PMID 40722349, 2025). "Microglia can also regulate post-stroke plasticity through other mediators such as microglia-neuron interactions mediated by the neural factors CD200 and CX3CL1." (PMID 34831273, 2021). "The chemokine fractalkine (CX3CL1) and its receptor CX3CR1 play a fundamental role in the pathophysiology of stroke." (PMID 29323156, 2018). "In view of the dispersed data related to CX3CL1/CX3CR1 and ischemic stroke it is difficult to judge the neuroprotective role of CX3CL1/CX3CR1 signaling and the future possibility to manipulate this pathway pharmaceutically to reduce the sequel of stroke." (PMID 30319362, 2018). "Silymarin raised cortical TNFα, IL4, IL10, IGF1, BDNF, and CX3CL1 levels in the HFD group with stroke, while the striatum did not present relevant differences." (PMID 39624169, 2024). "Other chemokines upregulated in the first 3 h after stroke are microglial response factor-1 (MRF-1), fractalkine (CX3CL1), and macrophage inflammatory protein 1 (MIP-1), which all contribute to the infiltration of the injured tissue with inflammatory cells and thus weaken the BBB." (PMID 35008440, 2021).
Cognitive impairment (29 papers, 2012 to 2025). Abnormal cognition is characterized by deficits in thinking, reasoning, or remembering. "Our work demonstrates a role for CX3CL1 in both cognitive and motor function and suggests that loss of CX3CL1 signaling is sufficient to induce cognitive impairment that is likely linked to deficits in both hippocampal neurogenesis and LTP." (PMID 32410624, 2020). "Two forms of CX3CL1 display differential activity in adeno-associated virus-treated CX3CL1 knockout mice; specifically, knocking out CX3CL1 leads to severe cognitive deficits, which can be mitigated by sCX3CL1 treatment, while mCX3CL1 can only partially alleviate them." (PMID 38674036, 2024). "In this study, we confirm that CX3CL1 deficiency was sufficient to induce cognitive impairment." (PMID 32410624, 2020). "Collectively, our data suggest that CX3CL1 signaling plays an important role in maintaining normal cognitive function in mice and demonstrates that a loss of CX3CL1 signaling could underlie the development of cognitive impairment." (PMID 32410624, 2020). "The authors evaluated the impact of soluble CX3CL1 expression on cognition in tau rTg450 mice after the onset of cognitive deficits by intraparenchymal injections of FKN in the ventricular system through adeno-associated virus serotype 4." (PMID 36614325, 2023). "In contrast, in a cerebral ischemia model, CX3CL1/CX3CR1 downregulation significantly reversed cognitive deficits by inhibiting microglia activation and promoting oligodendrocyte progenitor cell maturation and myelin regeneration." (PMID 37234914, 2023). "Lastly, it is worth mentioning that extensive evidence supports the role of CX3CL1/CX3CR1 axis disruption in neuronal damage leading to cognitive impairment and dementia in AD patients." (PMID 36233371, 2022). "In this study, we examined changes in CX3CR1 expression levels in the TF-induced POCD model and the potential therapeutic effect of CX3CL1 as a new treatment candidate for alleviating cognitive impairment by regulating inflammation." (PMID 33858422, 2021). "Here we analyzed the presence of CX3CL1, a chemokine expressed by neurons, in cerebrospinal fluid (CSF) samples from control subjects and patients with mild cognitive impairment and AD dementia." (PMID 30245615, 2018). "This seems important in aged hippocampal neurons, where the physiological decrease in CX3CL1 correlates with the cognitive impairment detected in older animals." (PMID 29361745, 2018). "Significant differences in CX3CL1 levels were detected in a cohort of 51 patients with mild cognitive impairment (MCI), 51 AD patients and 57 controls." (PMID 22919540, 2012). "Proinflammatory cytokines from the periphery, such as IL-6 or CX3CL1, could modify the response of microglia, increasing the proinflammatory environment and cognitive impairment." (PMID 40004217, 2025). "However, based on the complexity of the regulatory mechanism of cognitive impairment, it can be concluded that CX3CL1/CX3CR1 is only one of the factors affecting high-altitude-induced cognitive impairment." (PMID 37234914, 2023). "Chemokines CCL1, CCL2, CCL15, CCL27, CXCL9, CXCL10, and CX3CL1 might be most promising to serve as key molecular markers of cognitive impairment, although more cohort studies with larger populations are needed." (PMID 37291639, 2023). "The deficiency of CX3CL1 or CX3CR1 in AD models reduces β-amyloid deposition but increases tau phosphorylation and aggregation, with a consequent detrimental effect on the behavioral and cognitive deficit." (PMID 36092814, 2022). "Treatment with AAV-sFKN partially restored expression of both Ki67 and DCX in the SGZ, indicative of increased neurogenesis, suggesting that its ability to mitigate cognitive deficits in CX3CL1−/− mice could be dependent on this activity." (PMID 32410624, 2020).
Cognitive impairment (continued). "Included in the chemokines family, elevated CX3CL1 (fractalkine) plasma levels have been found in mild cognitive impairment (MCI) and mild AD patients, as well as an increase of CX3CL1 gene expression in the brains of AD patients in respect to control subjects, mainly in the early stage." (PMID 31766244, 2019). "However, a positive correlation between the plasma levels of soluble CX3CL1, and the course of AD and mild cognitive impairment has also been reported, providing an evidence for the involvement of soluble CX3CL1 in the pathogenesis of AD." (PMID 26441528, 2015). "Furthermore, they show that hTau mice expressing ckFKN (hTau/CX3CL1105Δ) had similar phospho-tau pathology and cognitive deficits as hTau; Cx3cl1−/− mice, both of which had significantly greater phospho-tau pathology and cognitive deficits than hTau mice expressing endogenous FKN." (PMID 30744705, 2019). "Studies using animal models have also indicated a link between CX3CL1/CX3CR1 and severity of depressive behavior and cognitive impairment." (PMID 35782435, 2022). "Our results highlight a variable pattern in urinary CX3CL1 levels across the cognitive impairment spectrum, with a notable decrease in aMCI patients, followed by an increase in those with AD." (PMID 39917031, 2025). "Although the association between CX3CL1/R1 signaling and POCD is established, the pathogenesis of postoperative cognitive impairment has not been elucidated." (PMID 33858422, 2021). "For example, increased level of Cx3cl1 was reported after HFD consumption and induced neuroinflammation-relevant process, while decreased Cx3cl1 expression in hippocampus and amygdala was reported in HFD-induced obese mice that showed significant cognitive deficits." (PMID 35942128, 2022). "Among others, IL-15, CX3CL1 and IL-6 were elevated in patients with minimal HE38, a cognitive impairment we did not assess, but which is likely present in our groups, and the markers could be correlated with both HE and death." (PMID 37973887, 2023).
lung carcinoma (27 papers, 2017 to 2025). "Additionally, CX3CL1 is associated with spinal metastasis in lung cancer patients and correlates with poor overall survival and CX3CL1 is also involved in metastasis of cancers originating in the bone." (PMID 37025604, 2023). "In a report analyzing lung cancer data from the Gene Expression Omnibus database and The Cancer Genome Atlas, CX3CL1 mRNA expression in lung adenocarcinoma tissue was decreased compared to healthy controls." (PMID 40508161, 2025). "Although studies on the role of CX3CL1 in lung cancer in humans are few, some have proposed CX3CL1 as a target molecule for immunotherapy." (PMID 41210693, 2025). "The relationship between bone metastasis and CX3CL1 in lung cancer patients has been reported in several studies." (PMID 40508161, 2025). "CX3CL1 is a crucial chemokine for recruiting TILs and high expression levels of CX3CL1 correlate with positive prognosis in colorectal, breast, and lung cancers." (PMID 39076974, 2024). "A previous study has also demonstrated that CX3CL1 promotes lung cancer cell migration and invasion by activating focal adhesion signaling." (PMID 39539669, 2024). "CX3C motif chemokine ligand 1 (CX3CL1) was considerably overexpressed in lung cancer and has the ability to promote the invasion and migration of lung cancer cells through the Src/focal adhesion kinase signaling pathway." (PMID 36090899, 2022). "The relationship between the expression of CX3CL1 and the pathological type and malignant degree of lung cancer will be explored, aiming to provide some ideas for CX3CL1 as a clinically diagnostic and prognostic indicator." (PMID 33191645, 2021). "Our group has confirmed that 100ng/ml of CX3CL1 can up‐regulate migrated and invasive abilities of lung cancer A549 cells and H520 cells." (PMID 33191645, 2021). "Since CX3CL1 is an exocrine small molecule protein that can be detected in serum, we will further collect serum samples from lung cancer patients in the next experiment." (PMID 33191645, 2021). "In this study, we focused on exploring the effect of soluble CX3CL1 in regulating lung cancer A549 and H520 cells." (PMID 33191645, 2021). "The expression of CX3CL1 was found to be increased in lung cancer with higher pathological grades and metastatic lymph nodes." (PMID 32219066, 2020). "This is supported by experiments in orthotopic implantation of lung cancer, where the antitumor effects of CX3CL1 were derived from natural killer cell activities." (PMID 28122354, 2017). "In human lung cancer, CX3CL1 is important for the development of bone metastasis 14,18." (PMID 41210693, 2025). "In future studies it will be important to analyze whether the pattern of CX3CL1 expression in lung cancer could be a differential marker between squamous cell lung cancer and other sub types of lung cancer." (PMID 41210693, 2025). "Although myeloid cells expression of CX3CL1:CX3CR1 may be linked to tumor-promoting activities such as enhanced growth and migration in lung cancer, CX3CL1:CX3CR1 expression in bulk level is a positive prognostic factor in patients with LUAD." (PMID 40474982, 2025). "Thus, there is an urgent need to expand basic research data on CX3CL1 in lung cancer, starting with characterization of its expression in human neoplastic lung tissue." (PMID 41210693, 2025). "Furthermore, increased expression of chemokine C-X3-C motif ligand 1 (CX3CL1), which is a known ligand for the CX3CR1 receptor present on NK cells, was found to be associated with improved overall survival of patients with lung cancer." (PMID 34439191, 2021). "In the next experiment, we will further explore the effect of membrane‐bound CX3CL1 on lung cancer to verify whether it is related to the colonization of lung cancer cells in the metastatic tissue." (PMID 33191645, 2021).